IRF8 (interferon regulatory factor 8)
Diseases named in the same sentence as IRF8 in open-access papers (continued):
Sharing a sentence is not in itself a finding about the gene and the disease.
infection (continued). "IRF8 is required for development of the dendritic cell lineages, IL-12 production by these cells (Th1 polarization of immune response), recruitment of T cells to the site of infection, macrophage activation and containment of infection by activated macrophages in granulomas." (PMID 21731497, 2011). "Interferon regulatory factor 8 (IRF8) is an activator of AMPK/mTOR signaling that mediates sterile inflammation and response to infection." (PMID 40507030, 2025). "Of the ISGs IFN-γ, IRF5, NMI, and IRF8, only the expression of IFN-γ changed during the course of infection." (PMID 39104769, 2024). "Specifically, rVHSV-P infection inhibited the expression of the IRF10, IRF8, IRF4A, and IRF1A IFN-related genes compared with rVHSV-wild infection." (PMID 33465148, 2021). "We also observed the mRNA expression of STAT1 and IRF8 to be high at 8 dpi upon infection by the RHΔCPSII strain, indicating the probability of activation of STAT1 and IRF8." (PMID 33519775, 2020). "In contrast to the positive role of IRF8 in EBV lytic replication observed in our study, most of the IRFs contribute to anti-viral immunity and block the infection or lytic reactivation of herpesviruses." (PMID 29357389, 2018). "During infection, 11% of total CD4+ T cells in MLN of B6 mice were GATA3+ while 12% of total CD4+ T cells expressed Foxp3 in infected Irf8-/- mice." (PMID 28968468, 2017). "During primary infection, MDSC expanded to a significantly greater extent in mesenteric lymph nodes (MLN) and spleens of Irf8-/- and BXH-2 than B6 mice." (PMID 28968468, 2017). "Among the several IRFs reported, we focused our study on IRF8 as it plays a major role in IFN signaling, response to infection, and maturation of myeloid lineages cells." (PMID 24885259, 2014). "IRF8 is a member of the Interferon Regulatory Factor (IRF) family of transcription factors that plays a central role in interferon signaling, response to infection and maturation of dendritic cells (DCs) and other myeloid lineages." (PMID 23853600, 2013). "However, IRF-8−/− mice showed percentages of pulmonary macrophages, DC, CD4+ and CD8+ T cells substantially similar to those of WT-B6 mice, suggesting an accelerated and compensatory pulmonary recruitment of these populations at early stage of infection in deficient animals." (PMID 23717393, 2013). "Dialysis patients who required hospitalization due to infections within one year of follow-up displayed significantly reduced IRF8 expression levels in pDCs compared to patients without such infections (p = 0.04)." (PMID 37508555, 2023). "Dialysis patients who developed infections requiring hospitalization within one year after the FACS analysis were characterized by elevated numbers of pDC, reduced expression of IRF8 in pDC, and slightly increased C-reactive protein (CRP) levels obtained parallel to the FACS analysis." (PMID 37508555, 2023). "IRF-8 could enhance the activation of IFN-γ-inducing genes, and therefore, participate in the consequent processes of infection." (PMID 35211408, 2022). "Surprisingly, despite reduced microglia/macrophage proinflammation markers in the Irf8−/− mouse brain, the absence of IRF8 did not prevent the development of neurological signs nor its prolonged survival upon infection." (PMID 34379515, 2021). "Strikingly, T. gondii infection resulted in the rapid accumulation of inflammatory IRF8+ DCs in WT mice and this population was virtually absent in Tbx21-/- mice by day 8 post-infection." (PMID 33465134, 2021). "Antiviral activity towards PRRSV and the IBV/PRRSV coinfection displayed upregulation of interferon regulatory factors (IRFs) that included IRF1, IRF4, IRF8, expressed in the PRRSV infection and IRF7 showing up in place of IRF1 in the coinfection in this study." (PMID 33187194, 2020). "IRF-8 expression in all myeloid subsets did not associate with age, CD4 count or nadir, CD8 count, CD4/CD8 ratio, or total self-reported years of infection or on ART (data not shown)." (PMID 31849969, 2019).
infection (continued). "Although IRF4 and IRF8 are also expressed in DCs, Syk expression was not affected by infection of IRF4 or IRF8 (data not shown), demonstrating that monomeric PU.1 transactivates the Syk gene in DCs in the same manner as that in MCs." (PMID 29386516, 2018). "Western blot analysis showed up-regulation of IRF4 but no observed change in IRF8 protein level after 0, 2, 4, 7 and 15 days of post-infection." (PMID 23658517, 2013). "To gain further insight into the genes, proteins and pathways that play a role during pathological neuroinflammation, and identify those whose expression is regulated by Irf8, we used transcript profiling of BXH2 and B6 brains either prior to or during PbA-infection." (PMID 23853600, 2013). "Herein, we report that, despite the high numbers of lung neutrophils in the early stages of infection, a protective immunity was not established in IRF-8−/− mice." (PMID 23717393, 2013). "More than half of the genes (n = 48) regulated by infection in BXH2 were common to the B6 set and may indicate Irf8-independent regulatory mechanisms." (PMID 23853600, 2013). "IRF8−/− mice do not produce IL-12p40, lack Th1 polarization (absence of antigen specific CD4+, IFNγ producing T cells), and are susceptible to in vivo infection with intracellular pathogens." (PMID 21731497, 2011). "Recent work of the Ozato laboratory identified interferon regulatory factor 8 (IRF8) as a positive regulator of autophagy in murine macrophages and DCs exposed to various stress signals, including starvation, exposure to TLR ligands or infection with Listeria monocytogenes." (PMID 29434592, 2018). "Infection with FV1 lpg2− did not significantly affect IRF8 expression." (PMID 26630499, 2015). "We concluded that Asah1 is not induced during infection or by IFN-I, however IRF8 regulates Asah1 expression during development of macrophages." (PMID 32165633, 2020). "Moreover, the absence of IRF8 expression in MHCII+CD11c+ DCs resulted in dramatically elevated parasite burden both at the site of infection and in the spleen on day 5 post infection." (PMID 33465134, 2021). "IRF8 is required for the optimal activation of the NLRC4 (NLR family CARD domain containing 4) and NLRP3 (NLR family pyrin domain containing 3) inflammasome activation after infection with Gram-negative bacteria to initiate inflammatory responses." (PMID 34067819, 2021). "Although IRF1 and IRF8 are known to cooperatively regulate IL12B gene transcription, we report that the FV1 lpg1− mutant does not affect IRF1 expression compared to WT at 8 hours post-infection." (PMID 26630499, 2015). "The down-regulation of genes involved in the interferon response (i.e. irf1, irf4 or irf8) in infected samples at 7 dpi (and lack of up-regulation of other interferon genes at this time point) suggests that ISAV modulates this process as part of its infection and replication strategy." (PMID 33985436, 2021). "However, it is not clear how IRF8 intrinsically/extrinsically affects NK cell function (that is impaired in IRF8−/− patients), or the formation and maintenance of the long-lived MCMV-specific NK cell memory compartment including protection against re-infection." (PMID 30546366, 2018).
cancer (65 papers, 2011 to 2026). A tumor composed of atypical neoplastic, often pleomorphic cells that invade other tissues. "High levels of IRF8 in cancer patients are significantly associated with the infiltration of activated effector CD8+ T cells." (PMID 41368628, 2025). "Between the two subsets of MDSCs, PMN-MDSCs exhibit more extensive expansion in cancer when compared to M-MDSCs, and a decrease in IRF8 has been associated with an increase in MDSC frequency in cancer." (PMID 36078039, 2022). "Hypermethylation of IRF8 promoter has been reported to underlie IRF8 silencing or downregulation in multiple cancers, including BC." (PMID 33766090, 2021). "Furthermore, IRF8 expression level is positively linked to cancer patient prognosis and response to immunotherapy." (PMID 36078039, 2022). "Besides regulation of innate immune responses, IRF8 has been implicated as a tumor suppressor gene in certain cancers." (PMID 31850068, 2019). "A deeper understanding of IRF-8’s mechanisms can provide insights into developing novel strategies for cancer treatment and personalized medicine." (PMID 41315179, 2025). "This heterogeneity manifests primarily in two distinct ways: IRF8 promotes oncogenesis in CSCs while suppressing it in differentiated common cancer cells, operating through completely opposite mechanisms." (PMID 41368628, 2025). "Like many other transcription factors, IRF8 can be dysregulated in cancer, and therefore, this study aimed to determine the protein expression of IRF8 in canine OSA." (PMID 38792023, 2024). "LEF1 expression has also been shown to be downregulated in numerous cancers through promoter hypermethylation and also higher levels of IRF8." (PMID 38792023, 2024). "Future studies are required to determine how IRF8 abundance and function are regulated in the context of cancer and PD-1-SHP-2 signaling." (PMID 36581713, 2023). "CD8+ cytotoxic T cells had elevated expression of the cytotoxic markers PD-1, Gzmb, Gzmk, Prf1, Nkg7, Eomes, Irf8, Klrd1, Fyn, Nfatc1, Tnfrsf9, and Zap70, supporting their killing function against cancer cells." (PMID 37762216, 2023). "IRF8 appears to impede the progression and formation of cancer by increasing the expression of tumor suppressor genes, such as Caspase 1, p21, p27, and PTEN." (PMID 36078039, 2022). "In this cell line, ectopic expression of IRF8 induced cell cycle G2/M arrest and apoptosis further supporting IRF8’s role in impeding cancer progression." (PMID 36078039, 2022). "In other cancer cell lines with a methylated IRF8 promoter, IFN-γ treatment showed decreased ability to induce IRF8 expression." (PMID 36078039, 2022). "Under pathological conditions such as cancer, Irf8 is silenced by its promoter DNA hypermethylation, resulting in accumulation of PMN-MDSCs and CD11b+ Ly6G+Ly6Clo monocytic MDSCs (M-MDSCs) in mice." (PMID 36078039, 2022). "Mechanistically, G-CSF was shown to downregulate the expression of the IRF8 transcription factor in DC precursors; and the low IRF8 expression in pre-DCs in cancer patients correlated with poor prognosis, indicating the relevance of such mechanisms in human." (PMID 36561751, 2022). "Taken together, these studies provide evidence for promoter methylation as a mechanism for IRF8 silencing in certain types of human cancer cells." (PMID 36078039, 2022). "To investigate the role of IRF8 in IRF8-dependent AML cancer cells in more detail, we selected six AML cell lines (THP1, MOLM13, MV4-11, NB4, HL60, and KG1α) and analyzed the expression of IRF8 in those cells." (PMID 33673123, 2021). "In several tissue types, such as in colon, pancreas, kidney, and stomach, we observed a significantly altered expression of IRF8 in cancer tissues compared to the corresponding normal tissues." (PMID 33673123, 2021). "To this end, we took advantage of a homemade TMA consisting of 24 ER-negative BC specimens, classified according to either low or high IRF8 cancer cell expression as determined by traditional immunohistochemistry." (PMID 33766090, 2021).
cancer (continued). "Mice defect in IRF-8 generate massive amount of MDSCs, while overexpression of IRF-8 led to depletion of MDSCs in murine models of carcinoma, indicating IRF-8 as a negative regulator in MDSC biology." (PMID 34512667, 2021). "We established that at least one mechanism by which STAT3 facilitates PMN-MDSC expansion in cancer models is IRF8-dependent by demonstrating a unique G-CSF-STAT3-IRF8 axis." (PMID 32983128, 2020). "Together, these studies expand our current knowledge on IRF8 and eIF4E-mediated regulation of IRF8 in the host defense against cancer." (PMID 32731503, 2020). "To determine if these changes also occur in human cancer patients, we analyzed IRF8 expression in human BM and found that IRF8 was downregulated in both BC and PDAC patients compared to healthy controls." (PMID 29593283, 2018). "In vivo, IRF8 is essential for Th9 cell generation and their biological functions in the context of cancer." (PMID 29233972, 2017). "Interferon Regulatory Factor-8 (IRF8) is constitutively expressed in monocytes and B cell lineages and plays important roles in immunity to pathogens and cancer." (PMID 27171004, 2016). "Since then, new functional roles for IRF8 have been identified in cancer biology beyond its prototypical link to hematologic malignancies, including its ability to regulate apoptotic death of various types of solid tumors." (PMID 26008967, 2015). "We therefore examined the sensitivity and specificity of cancer detection in urine by combining methylated ZNF671 with methylation of two other TSGs (IRF8 and sFRP1) using a previously published urine sample cohort (26 UCs and 19 non-cancerous controls)." (PMID 26320192, 2015). "For methylation detection in voided urine samples of cancer patients, the sensitivity and specificity of using any of the methylated genes (IRF8, p14 or sFRP1) by qMSP was 86.7% and 94.7%." (PMID 21599969, 2011). "Based on these findings, we speculate that IRF8 enhances cancer immunity and boosts the efficacy of anti-PD-1 therapy in GC by regulating Wnt/β-catenin and TGF-β signaling pathways." (PMID 39940857, 2025). "The intricate role of IRF-8 in cancer highlights its potential as a therapeutic target." (PMID 41315179, 2025). "Nevertheless, targeting the activation of IRF8 to inhibit MDSC formation may represent a novel strategy for cancer immunotherapy." (PMID 41368628, 2025). "Notably, the downregulation of IRF8 observed during the differentiation of MDSC in cancer lesions parallels that observed during the formation of Lin−c-Kit+Sca-1−FcγR+ GMP clusters during regenerative myelopoiesis." (PMID 41360769, 2025). "The mechanism may be that MDSC produces IL-10, which in turn promotes cancer initiation by regulating the STAT3-DNMT3b-IRF8 axis." (PMID 38319729, 2024). "IRF8 functions as a link between cancer and the immune system." (PMID 36078039, 2022). "One mechanism by which cancer cells may alter the expression of Fas, and thereby reduce sensitivity to apoptosis, is through downregulation of IRF8." (PMID 36078039, 2022). "IRF8 is also down-regulated in MDSCs of human cancer patients." (PMID 36078039, 2022). "In other cancer types, the transcriptional set-up may be different, which may lead to an alternative genomic distribution of IRF8, and thereby to a disparate role in gene regulation." (PMID 33673123, 2021). "In most non-AML cancer cells, including other hematopoietic cancer cells, IRF8 deletion is associated with a positive score, indicating that IRF8 deletion leads to an increased cell proliferation of the cells." (PMID 33673123, 2021). "A STAT3-C/EBPβ axis has been shown to impact PMN-MDSC biology in inflammation and cancer, but the role of non-coding RNAs and whether this axis interfaces with IRF8 requires further examination." (PMID 32983128, 2020). "Interestingly, negative regulators of enhancer-associated genes including the TFs CEBPA, IRF8, IRF1 and ETV6, can suppress cancer cell growths." (PMID 31665430, 2020).
cancer (continued). "Furthermore, it was shown that IRF8 regulates the expression of aCDase during the induction of apoptosis in cancer cells." (PMID 32165633, 2020). "IRF8, RTEL1, and FCGR3A mutations have been observed in NKD patients but their association with cancer is unknown." (PMID 31379882, 2019). "IRF8, RTEL1, and FCGR3A mutations are associated with NKD but their associations with cancer are unknown." (PMID 31379882, 2019). "We further demonstrated IRF8 downregulation during cancer reduces cDC1 development in the BM." (PMID 29593283, 2018). "Our results show that IRF8 complexes boost the Th9 program and repress Il4 expression to modulate Th9 cell differentiation, thereby implicating IRF8 as a potential therapeutic target to affect Th9 responses in cancer therapy." (PMID 29233972, 2017). "Also, aberrant methylation of the IRF8 gene in nasopharyngeal, esophageal and multiple other carcinomas has been reported." (PMID 25120651, 2014). "Thus, IRF8 may act distinctly in AML compared to other cancer types, which warrants further investigation." (PMID 33673123, 2021). "In myeloid cells, the top 50 pan-cancer central genes included seven genes involved in myeloid cell differentiation (CD4, FCER1G, IRF8, TYROBP, TLR2, TREM2 and ITGAM), but only two of them (FCER1G and TYROBP) were found among the top 50 DEGs." (PMID 36350625, 2023). "While the sensitivity and specificity of cancer detection using ZNF671 methylation alone was 57.7% and 89.5%, combining hypermethylation of ZNF671 with that of IRF8 and SFRP1 increased the sensitivity to 96.2%." (PMID 26320192, 2015). "Furthermore, the data indicated that IRF8 may have an important role in cancer pathogenesis." (PMID 25120651, 2014). "As compare to non-cancer group, higher methylation level of DAPK, IRF8, p14, RASSF1A and SFRP1 were detected in cancer samples." (PMID 21599969, 2011). "Thus, when the suppressor of OPN, interferon regulatory factor 8 (IRF8) is reduced, OPN expression is significantly increased, leading to immune evasion of cancer." (PMID 35590394, 2022). "Within non-hematopoietic cancer cells, IRF8 plays a protective role against the formation of a metastatic phenotype." (PMID 36078039, 2022). "The goal of the present study was to examine the relationship between IRF8 with the therapeutic response and the immune contexture in BC, since its clinical significance in this type of cancer has not been thoroughly addressed." (PMID 33766090, 2021). "The cancers have been observed in NKD patients with GATA2 and MCM4 mutations although not in patients with IRF8, RTEL1, and FCGR3A mutations." (PMID 31379882, 2019). "For early-stage cancers, DNA methylation-based biomarkers are of particular importance Recent scientific work indicates the high potential of hypermethylated genes TWIST1, VIM, ZNF671, OTX1, and IRF8 for early diagnosis and PTK2, AHNAK, and DAPK for BC prognosis." (PMID 39685620, 2024). "For example, many cancer types, including all desmoplastic small round cell tumors, Ewing sarcomas, synovial sarcomas, undifferentiated pleomorphic sarcomas, and all epithelial malignancies show a negative IRF8 expression." (PMID 37380989, 2023). "In the process of module analysis and characteristic molecular screening, we selected two characteristic modules and 10 characteristic molecules (PTPRC, CD2, CD69, IRF8, CCR7, CCL5, il2rb, CXCL10, CCR5, TBX21), which could be used as biomarkers of cancer stem-like cells for GIST patients." (PMID 34925310, 2021). "Therefore, enhancing Pak2 activity in myeloid progenitors may serve as a therapeutic target for future strategies aimed at increasing IRF8 expression and decreasing PMN-MDSC accumulation in cancer." (PMID 32983128, 2020).
cancer (continued). "IRF8 has been shown to be a key regulator of Fas-mediated apoptosis in various cancer cells and metastatic phenotypes in CRC cells; however, the correlation between TNF-α-induced apoptosis and IRF8 expression in CRC cells has not been investigated." (PMID 25495942, 2014). "Furthermore, the transcription factors PU.1, IRF8, and BATF3 were also utilized to reprogram cancer cell lines into nonadherent cultured spheroids." (PMID 41368628, 2025). "As we were able to identify a putative pro-proliferative and negative prognostic role of IRF8 in AML, we hypothesized that IRF8′s role in AML might vary from its function in other cancer types." (PMID 33673123, 2021).